OR2G2 (olfactory receptor family 2 subfamily G member 2)
Description:
Odorant receptor.
Synonyms: OR1-32
Tractability: Antibody: UniProt places it where antibodies can reach, with medium confidence; UniProt predicts a signal peptide or a membrane-spanning region; its Gene Ontology location is reachable by antibodies, with medium confidence.
Gene: Protein-coding gene on chromosome 1 (247,588,360 to 247,589,313, forward strand). Ensembl gene ENSG00000177489.
Subcellular location: Cell membrane
Pathways (Reactome):
Sensory Perception: Expression and translocation of olfactory receptors
Gene Ontology:
Molecular function: olfactory receptor activity; G protein-coupled receptor activity
Biological process: detection of chemical stimulus involved in sensory perception of smell; G protein-coupled receptor signaling pathway
Cellular component: plasma membrane; membrane
Genetic constraint (gnomAD): Loss-of-function variants: 0 observed, 0.17 expected, observed/expected ratio (o/e) 0, 90% interval 0 to 1.88. That is too few expected variants to judge how well the gene tolerates losing a copy. Missense variants: 456 observed, 406.23 expected, observed/expected ratio (o/e) 1.12, 90% interval 1.04 to 1.21. Synonymous variants: 174 observed, 159.62 expected, observed/expected ratio (o/e) 1.09, 90% interval 0.96 to 1.24.
Homologues: Orthologues: pig OR2G2 (83% identical). Paralogues in human: OR2G6 (64% identical), OR2G3 (61% identical), OR2C3 (58% identical), OR2W3 (57% identical), OR2B2 (56% identical), OR2H2 (56% identical), OR2C1 (55% identical), OR2J2 (55% identical), OR2B6 (55% identical), OR2W1 (55% identical), OR2B3 (54% identical), OR2H1 (54% identical), and 80 more.